MYC (MYC proto-oncogene, bHLH transcription factor)
Diseases named in the same sentence as MYC in open-access papers (continued):
Sharing a sentence is not in itself a finding about the gene and the disease.
lymphoma (continued). "Diffuse large B-cell lymphoma (DLBCL) with MYC alteration is classified as high-grade B-cell lymphoma with MYC and BCL2 and/or BCL6 rearrangements (double/triple-hit lymphoma; DHL/THL), DLBCL with MYC rearrangement (single-hit lymphoma; SHL) and DLBCL with MYC-cluster amplification (MCAD)." (PMID 36497332, 2022). "The high-activity MYC group was enriched for DE (p < 0.00001) and ABC-type (p < 0.00001) lymphoma." (PMID 35267654, 2022). "The lymphoma subtype at the time of transformation was DLBCL in 13 patients and high-grade B-cell lymphoma not otherwise specified in 5 patients (of which 1 patient was with MYC and BCL2 rearrangements, considering a double-hit lymphoma)." (PMID 36185179, 2022). "Patients with co-expression of MYC and BCL2 but without underlying rearrangement, as defined by immunohistochemistry (IHC), are commonly referred to as double-expressor (DE) lymphoma." (PMID 35198451, 2022). "Lymphomas with two oncogenic translocations other than MYC (e.g. concomitant Bcl-2 and Bcl-6 translocations without a MYC breakpoint) or other gene translocations associated with MYC translocations (e.g. CCND1 translocations) are not included in this category." (PMID 36618391, 2022). "Therefore, the so-called “grey zone lymphomas” category has been removed and replaced with two new categories: “HGBL with MYC and BCL2 and/or BCL6 rearrangements”, or “HGBL-DH/TH”, and “HGBL not otherwise specified” (HGBL, NOS)." (PMID 34283060, 2021). "Furthermore conditional deletion of MRE11 in B-lymphocytes prevented the development of IgH–MYC translocated lymphomas and triggered conspicuous DDR responses, suggesting that MRE11 counteracts MYC-induced RS." (PMID 34201047, 2021). "MYC is rearranged, amplified, or otherwise overexpressed in multiple types of non-Hodgkin’s lymphoma, including ~100% of Burkitt’s (BL), 30% of diffuse large B-cell (DLBCL), and >50% of mantle cell (MCL) lymphomas." (PMID 34577013, 2021). "A phase III randomized study (SWOG S9704) found that there was a trend favouring outcomes after consolidative auto‐HSCT in double protein‐expressing lymphoma (DPL) and MYC protein overexpressing patients, whereas all DHL patients have died irrespective of HSCT." (PMID 34698437, 2021). "Consistent with a role for translational activation in these aggressive lymphomas, we observe in a small cohort (n = 34) of MYC+/BCL2+ a clear correlation between MYC and BCL2 status and phosphorylation of ribosomal protein kinase p70S6K, an indicator of translation activation." (PMID 33562682, 2021). "Treatment with CS2164 greatly reduced the expression levels of MYC protein, implying that MYC might be a potential target for the antitumoral effectiveness of CS2164 in MYC-altered lymphomas." (PMID 33777762, 2021). "Importantly, the authors extend their findings on MYC, ZDHHC11/B, MYB upregulation, and mir-150 downregulation also to other lymphoma entities including cHL." (PMID 33544339, 2021). "BET inhibitor (BETi), JQ1, also limited PD-L1 transcription by decreasing BRD4 occupancy at CD274 promoter without changes in MYC occupancy in lymphoma." (PMID 34088360, 2021). "By targeting MYC, JQ1 showed anticancer activity in several cancer types including Merkel cell carcinoma, esophageal squamous cell carcinoma, and EBV-positive nasopharyngeal carcinoma, as well as in a variety of leukemias and lymphomas." (PMID 33801599, 2021).
lymphoma (continued). "The dual inhibitory mechanism of BR101801 in double-hit lymphoma cells, downregulates the MYC stability regardless of its translocation, amplification, and overexpression." (PMID 34372899, 2021). "High-grade B-cell lymphoma with MYC and BCL2 and/or BCL6 rearrangements, so called double-hit and triple-hit (DH/TH) lymphomas, are defined in the 2016 World Health Organization (WHO) classification as a new diagnostic category and includes a subset of tumors with DLBCL morphology." (PMID 34282799, 2021). "MYC protein expression has been shown to be a poor prognostic factor in the rituximab era, which is compounded by BCL2 co-expression (double-positive or double-expressor lymphomas)." (PMID 34404436, 2021). "Moreover, overexpression of BFL-1 enhances the resistance of c-MYC- and BCL2-expressing double-hit lymphomas to venetoclax, while its downregulation sensitizes them to apoptotic stimuli." (PMID 34576319, 2021). "High-grade large B cell lymphomas with concurrent MYC and BCL2 (or BCL6) translocations, previously known as double-hit (DHL)/triple-hit lymphomas, represent a rare category of tumors that is now recognized as a separate provisional entity in the revised WHO classification." (PMID 34456919, 2021). "Here, we investigated whether ectopic expression of c-MYC and BCL2 in different stages of B cells could lead to lymphoma and generate a mouse model for DEL." (PMID 32695674, 2020). "In addition, MYC regulates metabolic functions attributed to PML, including fatty acid β oxidation and its inhibition induces cellular senescence in lymphoma, osteosarcoma, and hepatocellular carcinoma." (PMID 31570853, 2020). "While ICB protected 18–30% of λ-MYC mice from lymphoma and death, all ICB-treated λ-MYC." (PMID 32165639, 2020). "MYC and MAX expression in lymphoma-derived cell lines was assessed by western blotting." (PMID 32587329, 2020). "Patients with SH and DE lymphomas have a prognosis in between DLBCL patients without MYC overexpression and patients with DH or TH HGBL." (PMID 33092116, 2020). "This link between c-MYC-driven cancers and a dependency on MCL-1 was confirmed by genetic studies, where heterozygous deletion of MCL-1 resulted in diminished growth of c-MYC-driven lymphomas." (PMID 33308268, 2020). "Given the importance of MYC deregulation in human leukemia and lymphoma, it is not surprising that its correct modulation is essential throughout the whole B lymphocyte development." (PMID 32102485, 2020). "One of main limitations of the successful treatment of MYC/BCL2 DH lymphoma is lack of comprehensive understanding of disease pathogenesis and mechanisms of chemotherapeutic resistance, as well as knowledge of potential therapeutic targets." (PMID 32459397, 2020). "The establishment of this model may provide a valuable tool to study the pathogenesis and treatment of c-MYC and BCL2 double-expressor lymphoma." (PMID 32695674, 2020). "Based on these results and in the light of the current World Health Organization (WHO) classification of lymphoma the diagnosis was revised toward “high-grade B-cell lymphoma with MYC and BCL2 rearrangements, Burkitt morphology”, commonly referred to as “double-hit lymphoma”." (PMID 33339535, 2020). "MAX mRNA expression in ALCL cases was significantly lower than that in other T-cell lymphomas (angioimmunoblastic T-cell lymphoma, adult T-cell leukemia/lymphoma, and extranodal natural killer/T-cell lymphoma, nasal type), regardless of MYC mRNA expression." (PMID 32587329, 2020). "The overproduction of EIF4E2 AAb in lymphoma patients may inhibit the downstream translation of oncogenic proteins like VEGF, MYC, cyclins, and STAT1." (PMID 32483460, 2020). "Indeed, TRIB3 interacted with MYC in Raji cells, which was supported by the colocalization of TRIB3/MYC in human lymphoma cells." (PMID 33298911, 2020).
lymphoma (continued). "Thus, in light of the current WHO classification, the diagnosis was revised to high-grade B-cell lymphoma with MYC and BCL2 rearrangement, Burkitt morphology (so-called “double-hit” lymphoma)." (PMID 33339535, 2020). "Given the highly proliferative nature of DLBCL with MYC/BCL2-DH, these high-grade lymphoma cells may frequently efface the low-grade FL lesion, potentially leading to its underdetection." (PMID 31844144, 2020). "Further, MYC, TRIB3, and MAX formed the heterotrimer in lymphoma cells." (PMID 33298911, 2020). "Collectively, these findings demonstrate that RIPK3, and by extension necroptotic cell death, is not a major suppressor of MYC-driven lymphoma development." (PMID 32555451, 2020). "Concurrent overexpression of the MYC and BCL2 protein without underlying evidence for gene translocations is known as a “double-expressor” (DE) lymphoma." (PMID 33092116, 2020). "Combinations of MYC with other oncogenes including RAS, oncogenic EBV components, or MYC-surface CD19 signaling amplification loops have been shown to accelerate lymphoma development." (PMID 32549409, 2020). "Overall, our finding suggests that MYC-expressing lymphoma cells are most probably addicted to the MYC-oncogenic effect and rely on MYC for their growth regardless of MYC rearrangements." (PMID 31288832, 2019). "When combined with MYC, NCCN-IPI and SUVmax single highest in the multivariate analysis, necrosisPET had the highest significance in predicting death due to lymphoma and a higher prognostic impact than NCCN-IPI, the currently most accurate prognostic index for DLBCL." (PMID 31028445, 2019). "We show that DZNep inhibits proliferation and induces apoptosis of these cell lines independent of the type of lymphoma, the EZH2 mutation status and the MYC, BCL2 and BCL6 rearrangement status." (PMID 31419226, 2019). "Development of lymphoma cell lines from LMP2A/MYC and MYC transgenic mice." (PMID 30135222, 2018). "Interestingly, Eμ‐MYC/Vav‐BCLX DT tumours appeared more variable by showing IgM−, IgM+ and mixed phenotypes consisting of IgM+ and IgM− lymphoma cells respectively." (PMID 29498802, 2018). "MYC, HDAC3, and PRC2 were demonstrated to form a repressive complex tethered to miR-29 and miR-26a promoter elements to epigenetically repress transcription of these miRNAs in MYC-expressing lymphoma cells." (PMID 30038718, 2018). "The decreases in the masses of spleens and tumors in the mice that had received MYC primary lymphoma cells were also significant but not as dramatic as in the mice receiving LMP2A/MYC cells." (PMID 30135222, 2018). "We describe a case of composite lymphoma consisting of chronic lymphocytic leukemia/small lymphocytic lymphoma (CLL/SLL), follicular lymphoma (FL) and high-grade lymphoma with MYC and BCL2 rearrangements (formerly and more colloquially denoted “double-hit” lymphoma)." (PMID 29793519, 2018). "Although the role of MYC in lymphomas’ lipids regulation has not been completely elucidated yet, the analysis of lipid pattern expression has shown different profiles between the MYC overexpressing ones and the others." (PMID 29937761, 2018). "Even though no baseline pS6RP was detected in either LMP2A/MYC or MYC lymphoma cells, S6RP phosphorylation was robustly observed with 5 μM TAK-659 treatment starting at 4 h only in the MYC lymphoma cells." (PMID 30135222, 2018). "Similar to over-expression of pro-survival BCL2-like proteins, loss of BH3-only proteins is not overtly oncogenic but can dramatically accelerate lymphoma development in the context of elevated MYC." (PMID 29769323, 2018). "The involvement of PI3K, c-MYC and MAPK pathways on glucose uptake, expression of glycolysis-associated genes and cell proliferation in lymphoma is not known yet." (PMID 28724379, 2017). "The treatment with Cdk1 inhibitors is consistently effective also in MYC-dependent mouse lymphoma and hepatoblastoma tumors, suggesting that RSV may be a potential new drug targeting MYC oncogenic pathway." (PMID 28555002, 2017).
lymphoma (continued). "Many studies reported lymphomas with clinical, histologic, immunophenotypic, or gene expression features of BL, but no detectable MYC translocation by FISH analysis." (PMID 29250206, 2017). "The mBL cases consisted mostly of “MYC-simple” lymphomas, while the non-mBL cases were predominantly “MYC-negative” lymphomas." (PMID 28379189, 2017). "The mBL or “MYC-simple” showed significantly improved five-year survival rate compared to the non-mBL or intermediate lymphomas." (PMID 28379189, 2017). "The large B-cell lymphomas with c-MYC and either BCL2 or BCL6 rearrangements are subsequently termed double-hit lymphomas (DHL), while those with all three rearrangements are referred to as triple-hit lymphomas (THL)." (PMID 28379189, 2017). "Therefore, DHL defined cytogenetically by c-MYC and BCL2 rearrangements comprise both de novo and secondary lymphomas transformed from FL." (PMID 28379189, 2017). "DLBCLs with co-expression of c-MYC and BCL2 are termed “double-expressor lymphomas” and most do not have concurrent c-MYC and BCL2 gene rearrangements." (PMID 28379189, 2017). "In 76 patients, they found extra copies of MYC, including 43 cases of double or triple extra copies; 105 patients had MYC-rearrangement (R) including 56 double- or triple-hit lymphoma, and 482 had no MYC abnormality (MYC normal)." (PMID 29057015, 2017). "In this study we showed regulation of glucose uptake by c-MYC- and PI3K/AKT/mTOR dependent pathways in lymphoma cell lines and demonstrated evidence for the altered glucose metabolism as a potential target to improve inhibitor-based therapeutic approaches in these cells." (PMID 28724379, 2017). "Notably, DHLs or triple-hit lymphomas are classified in the new category of ‘high-grade B-cell lymphoma (HGBL), with rearrangements of MYC and BCL2 and/or BCL6’ in the 2016 updated WHO classification." (PMID 27606052, 2016). "In addition, there is no direct evidence supporting critical oncogenic cooperation between MYC and BCL6 translocation in lymphoma development." (PMID 27347428, 2015). "More recently, MYC/BCL6 rearrangement lymphomas have been reported to be more frequently CD10 negative with IRF4/MUM1 positive, and cytogenetically less complex than MYC/BCL2 rearrangement lymphomas." (PMID 26416427, 2015). "Twenty-four-hour treatment of λ-MYC lymphoma cells with increasing amounts of PV1019 led to progressive reduction of MYC protein level, without affecting the stability of the protein." (PMID 26555894, 2015). "Remarkably, Pten was not downregulated in established λ-MYC lymphomas upon acute perturbation of miR-17-19b levels." (PMID 26555894, 2015). "Mouse #5 with MYC and PIM2 proto-oncogenes showed enlarged spleen and extensive lymphoma." (PMID 26606454, 2015). "Recently, increasing attention has been given to a subset of mature B-cell lymphomas with both MYC and BCL2 rearrangements, which have been defined as “double hit” lymphomas (DH lymphomas) because of their aggressive clinical course and resistance to conventional chemotherapy." (PMID 26517511, 2015). "Increased copies of chromosome 8 have been shown to correlate with increased MYC transcripts in certain myeloid malignancies, but this relationship has not yet been established in lymphomas." (PMID 25479599, 2014). "Though high expression is restricted to BLs, MYC target expression varies on a lower level across non-BL and intermediate lymphomas and constitutes a negative prognostic marker in these lymphomas." (PMID 24466310, 2014). "Rearrangement of BCL6 and MYC was detected in three patients, all of whom had nodal lymphomas with non-GC phenotypes." (PMID 24887414, 2014). "Pearson correlation coefficient for expression analysis of the Lymphoma/Leukemia Molecular Profiling Project (LLMPP) demonstrated Aurora A and B are highly correlated with MYC in DLBCL and mantle cell lymphoma (MCL), while both Auroras correlate with BCL2 only in DLBCL." (PMID 24893165, 2014).
lymphoma (continued). "When 2.5x105 spleen cells were incubated with 1x104 291PC lymphoma cells (E:T ratio 0.08-0.23:1 with respect to multimer-binding CD8+ T-cells), we did not observe any secretion of IFNγ although these cells express human c-MYC." (PMID 24130880, 2013). "Three of eight lymphoma cell lines (but no BL line) showed moderate (HT) to high CYCLON overexpression in the absence of marked MYC overexpression, thus suggesting the existence of alternate routes to CYCLON overexpression in these cells." (PMID 23828858, 2013). "In the conditions used for these assays, lymphoma cells that showed coincident CYCLON and MYC deregulation (Raji, B593, SUDHL4 cells, respectively) were sensitive to both Rituximab-induced, complement-mediated cytotoxicity and direct killing while the remaining cell lines were resistant." (PMID 23828858, 2013). "In keeping with previous reports, JQ1 treatment induced pronounced, dose-dependent MYC suppression in MYC-overexpressing lymphoma cells (Raji, B593, SUDHL4) while suppressive effects were more subtle in the lymphoma cell lines with lower starting levels of MYC (HT, OCI-Ly3 and Ly10)." (PMID 23828858, 2013). "OVA- and/or GFP-expressing lymphomas were rejected at a dose of 1×105 cells without prior immunization, but human c-MYC-expressing lymphomas were not rejected." (PMID 22479645, 2012). "After transfer into wild-type mice 60–70% of systemically growing lymphomas expressing all three antigens were rejected; lymphomas expressing only human c-MYC protein were not rejected." (PMID 22479645, 2012). "Since the MYC fusion is very likely to be the first event in lymphoma development, complex karyotypes are indicators of disease progression and inferior outcome and do not indicate an IG-MYC fusion as a secondary event in children." (PMID 22548066, 2012). "High levels of MCL1 were found in solid human tumors and cell lines derived from human leukemia or lymphomas; furthermore, studies in vivo showed that knockdown of NOXA or co-expression of MCL1 and oncogene MYC can significantly accelerate the development of tumors such as lymphoma or leukemia." (PMID 22548841, 2012). "Moreover, the presence of combined MYC dysregulation, and BCL2 upregulation at diagnosis already predicted a very aggressive clinical course with rapid transformation into a high-grade lymphoma." (PMID 21736761, 2011). "Similarly, in lymphoma, overexpression of RUNX2 and MYC results in the "collaboration" of the two corresponding proteins to attenuate apoptosis and promote proliferation." (PMID 20465837, 2010). "In contrast, despite the fact that LM, LR, and LMR lymphomas all regress upon MYC and/or K-rasG12D inactivation, phospho-Stat5 decreased upon MYC, but not K-rasG12D or dual MYC/K-rasG12D inactivation." (PMID 18461184, 2008). "MYC and RUNX3, which are regulators of cellular processes such as proliferation and differentiation, were among the transcription factors with indirect effects in lymphomas." (PMID 18358079, 2008). "In addition to the potential correlation between c-MYC and the frequent gain of CFA 13 in canine lymphoma, the present report identifies several other possible evolutionary counterparts of aberrations found in human NHL." (PMID 14562028, 2003). "Multiple factors, such as EZH2, c-MYC, IKZF1, IKZF3, IRF4, and CDK6, which are essential for the proliferation and survival of malignant plasma cells and lymphoma, were decreased upon treatment with PM in all tested MM and lymphoma cell lines, including MM1S, MM1R, and TMD-8." (PMID 40562746, 2025). "Because many AMLs express high levels of MYC, which is an important negative prognostic factor, we wondered whether AMLs, like MYC-driven lymphomas, are dependent on MNT for sustained cell survival and expansion." (PMID 41140443, 2025).